CCNB1 (cyclin B1)
Description:
Essential for the control of the cell cycle at the G2/M (mitosis) transition. Binds and activates cyclin-dependent protein kinase CDK1/CDC2.
Synonyms: CCNB
Tractability: Small molecule: a structure with a bound ligand is known; a high-quality ligand is known; it belongs to a druggable protein family. PROTAC: UniProt records ubiquitination sites on it; ubiquitination databases record sites on it; a small molecule that binds it is known.
Target class: Other cytosolic protein
Gene: Protein-coding gene on chromosome 5 (69,167,004 to 69,178,372, forward strand). Ensembl gene ENSG00000134057.
Subcellular location: Cytoplasm; Nucleus; Cytoplasm, cytoskeleton, microtubule organizing center, centrosome
Subcellular location (Human Protein Atlas): Cytosol
Pathways (Reactome):
Cell Cycle: APC/C:Cdc20 mediated degradation of Cyclin B; Activation of NIMA Kinases NEK9, NEK6, NEK7; Chk1/Chk2(Cds1) mediated inactivation of Cyclin B:Cdk1 complex; Condensation of Prometaphase Chromosomes; Condensation of Prophase Chromosomes; Cyclin A/B1/B2 associated events during G2/M transition; Depolymerization of the Nuclear Lamina; E2F-enabled inhibition of pre-replication complex formation; G2/M DNA replication checkpoint; Golgi Cisternae Pericentriolar Stack Reorganization; Initiation of Nuclear Envelope (NE) Reformation; MASTL Facilitates Mitotic Progression; Mitotic Prophase; Nuclear Pore Complex (NPC) Disassembly; Phosphorylation of Emi1; Phosphorylation of the APC/C; Polo-like kinase mediated events; Regulation of APC/C activators between G1/S and early anaphase; Regulation of PLK1 Activity at G2/M Transition; Resolution of Sister Chromatid Cohesion; The role of GTSE1 in G2/M progression after G2 checkpoint
Gene expression (Transcription): Transcriptional regulation by RUNX2
Developmental Biology: Regulation of MITF-M-dependent genes involved in cell cycle and proliferation
Disease: Nuclear events stimulated by ALK signaling in cancer
Gene Ontology:
Molecular function: cyclin-dependent protein serine/threonine kinase activator activity; patched binding; protein binding; protein kinase binding; ubiquitin-like protein ligase binding; cyclin-dependent protein serine/threonine kinase regulator activity
Biological process: mitotic metaphase chromosome alignment; mitotic spindle organization; positive regulation of attachment of spindle microtubules to kinetochore; positive regulation of G2/M transition of mitotic cell cycle; positive regulation of mitochondrial ATP synthesis coupled electron transport; positive regulation of mitotic cell cycle; regulation of mitotic cell cycle spindle assembly checkpoint; G2/M transition of mitotic cell cycle; cellular response to fatty acid; cellular response to hypoxia; cellular response to iron(III) ion; digestive tract development; mitotic cell cycle phase transition; negative regulation of gene expression; oocyte maturation; positive regulation of cardiac muscle cell proliferation; positive regulation of mRNA 3'-end processing; protein-containing complex assembly; regulation of chromosome condensation; response to DDT; response to mechanical stimulus; response to toxic substance; response to xenobiotic stimulus; spermatogenesis; tissue regeneration; and 1 more
Cellular component: centrosome; cyclin B1-CDK1 complex; cytoplasm; cytosol; mitochondrial matrix; nucleus; outer kinetochore; spindle pole; microtubule organizing center; nucleoplasm; membrane
Genetic constraint (gnomAD): Loss-of-function variants: 18 observed, 34.37 expected, observed/expected ratio (o/e) 0.52, 90% interval 0.36 to 0.78. The upper end of that interval is the gene's LOEUF score, 0.78, which puts it in group 3 of 6, group 1 being the genes least tolerant of losing a copy. Missense variants: 399 observed, 458.32 expected, observed/expected ratio (o/e) 0.87, 90% interval 0.8 to 0.95. Synonymous variants: 163 observed, 159.26 expected, observed/expected ratio (o/e) 1.02, 90% interval 0.9 to 1.17.
Homologues: Orthologues: chimpanzee CCNB1 (99% identical), macaque CCNB1 (99% identical), pig CCNB1 (91% identical), dog CCNB1 (91% identical), guinea pig Ccnb1 (89% identical), mouse Ccnb1 (86% identical), rat Ccnb1 (84% identical), zebrafish ccnb1 (60% identical), tropical clawed frog ccnb1 (56% identical), Drosophila melanogaster CycB (37% identical), Caenorhabditis elegans cyb-1 (26% identical), Caenorhabditis elegans cya-1 (24% identical), and 9 more. Paralogues in human: CCNB2 (50% identical), CCNA2 (28% identical), CCNB3 (27% identical), CCNA1 (26% identical), CCNF (22% identical), CCNE2 (21% identical), CCNE1 (21% identical), CCNO (17% identical), CCND3 (15% identical), CCND2 (15% identical), CCNJ (15% identical), CCNP (15% identical), and 6 more.
Diseases named in the same sentence as CCNB1 in open-access papers:
CCNB1 is named in the same sentence as 228 diseases in open-access papers, as found by Europe PMC text mining. Sharing a sentence is not in itself a finding about the gene and the disease. The quoted sentences say what the papers report.
breast carcinoma (236 papers, 2005 to 2026). "Overexpression of cyclin B1 can initiate uncontrolled cell growth and has been linked to aggressive tumor behavior with increased lymphovascular invasion in breast cancer." (PMID 38429789, 2024). "Recent research has shown that a higher expression of CCNB1 is linked to a poorer prognosis in certain cancers, such as gastric cancer, breast cancer, and non-small-cell lung cancer." (PMID 38581717, 2024). "Current research has implicated CCNB1 in the progression of various types of cancer, including gastric cancer, breast cancer, and non-small cell lung cancer." (PMID 38581717, 2024). "Second, in multiple breast cancer cell lines with high A3B, expression levels were observed to oscillate throughout the cell cycle and again associate with Cyclin B1." (PMID 37190094, 2023). "Cyclin B1 (CCNB1) was previously determined as being associated with LVI using large cohorts of breast cancer (BC) and artificial neural network (ANN) technique." (PMID 36418517, 2023). "Our study found a positive association between TMB and CCNB1 expression in breast cancer, specifically in luminal A BC." (PMID 36040381, 2022). "CCNA2 and CCNB1 are prognostic markers for ER +ve breast cancer and are closely associated with hormone therapy resistance." (PMID 34981672, 2022). "Upregulation of cyclin B1 has been associated with poor prognosis in hormone receptor-positive, luminal B and basal-like breast cancers." (PMID 25385471, 2015). "It has been reported that cyclin B1 was associated with recurrence in hepatocellular carcinoma, poor prognosis in gastric cancer, and poor survival in breast cancer." (PMID 24860838, 2014). "miR-379 has a predicted binding site on a key gene associated with breast cancer, Cyclin B1, which is known to be up-regulated and associated with poor patient outcome." (PMID 23874748, 2013). "This study suggests high cyclin B1 associates with aggressive phenotype and is an independent prognostic factor in breast cancer." (PMID 19293801, 2009). "Others have also found an association between cyclin B1 overexpression and poorer survival in breast cancer." (PMID 19615042, 2009). "In breast cancer, overexpression of cyclins A and E has been associated with poor prognosis and cyclin B1 with tumour grade, Ki-67, mitoses and adverse clinical outcome." (PMID 19615042, 2009). "Our study is the largest so far showing the association of high cyclin B1 and shorter survival in breast cancer." (PMID 19293801, 2009). "Notably, cyclin B1 (CCNB1), which has been reported as a key gene implicated in breast cancer brain metastasis,was also found to exhibit elevated sialylation levels in our Western blotting experiments." (PMID 41333208, 2025). "Additionally, CCNB1 overexpression is associated with aneuploidy and increased proliferation in human mammary carcinomas." (PMID 39795587, 2024). "Thus far, the observations indicate that A3B expression in breast cancer cells requires proliferation and associates strongly with Cyclin B (CCNB1 expression), indicative of the G2/M phase of the cell cycle." (PMID 37190094, 2023). "In addition, CCNB1 is considered a potential diagnostic biomarker for rhabdomyosarcoma and estrogen receptor (ER)-positive breast cancer." (PMID 36984548, 2023). "In addition to PLK1, PGCCs up-regulated CDC20 and CCNB1, which are associated with aneuploidy/polyploidy, adverse clinical outcomes of breast cancer patients, and resistance to adjuvant therapy." (PMID 38129519, 2023). "Additionally, the finding strengthens the anti-tumor potential of d-limonene suggesting its use as a chemotherapeutic and chemo-preventive drug in the treatment of breast cancer, particularly in tumors associated with Cyclin B1 and c-Myc over expression." (PMID 36307489, 2022).
breast carcinoma (continued). "Remarkably, previous studies have revealed that the upregulated expressions of CDK1 and CCNB1 are correlated with the worse OS in the basal subtype breast cancer, while CDC20, CCNB1, and CDK1 could act as diagnostic and prognostic markers in breast cancer." (PMID 34646403, 2021). "The chromosomal instability and invasiveness of breast cancer might be caused by the high expression of CCNB1, which usually precedes immobilization and aneuploidy of tumor cells." (PMID 33628185, 2020). "Considering this strategy, we also provided evidence that modulating mitotic progression and cyclin B1 expression could be therapeutically beneficial in the treatment of BRCA1-associated breast cancer." (PMID 30327455, 2018). "The results obtained in the current study using this mouse simulation system suggest that targeting of mitosis and cyclin B1 could be a useful strategy for treating BRCA1-associated breast cancer." (PMID 30327455, 2018). "CCNB1 protein levels have been shown to differ between breast cancer subgroups, tumors of different histological grade, and to be associated with breast cancer outcome." (PMID 21445301, 2011). "For example, RNMT (RNA guanine-7 methyltransferase) demonstrated an association with CDK1-cyclin B1 to sync mRNA G1 phase transcription and impact mRNA surveillance and it has also been found to potentially correlate with immune cell infiltration in breast cancer (BC)." (PMID 38735973, 2024). "Furthermore, breast cancer cell line synchronization studies indicate that A3B expression levels oscillate throughout the cell cycle in a manner that associates positively with Cyclin B1 (G2/M phase) and negatively with Cyclin E (G0/G1 phase)." (PMID 37190094, 2023). "Cellular assays demonstrated that C1orf112 promotes breast cancer proliferation by influencing cell cycle regulation, involving key molecules such as CCNB1 (cyclin B1)." (PMID 41878691, 2026). "Cellular experiments confirmed that DSN1 promotes breast cancer proliferation by affecting cell cycle pathways, involving key molecules such as CCNB1, CCND1, CKD1, CDK4, and CDK6." (PMID 41640445, 2026). "CCNB1 is significantly enriched in the cell cycle pathway and is highly expressed across multiple breast cancer subtypes, including luminal A, luminal B, HER2-positive, and TNBC." (PMID 40092695, 2025). "Our study revealed strong positive correlations between KPNA2 and FOXM1, CCNB1, and CCNB2 expression, with a significant association with the G2/M checkpoint pathway in breast cancer patients." (PMID 40002266, 2025). "The FOXM1 directly binds to and regulates CCNB1/CCNB2 promoters for breast cancer cell cycle progression, while KPNA2 modulates this process through its effects on FOXM1 nuclear transport and retention." (PMID 40002266, 2025). "Another study suggested that cell cycle analysis revealed that NUF2 induced G0/G1 cell cycle arrest by inhibiting cyclin B1 expression in breast cancer." (PMID 40220284, 2025). "Meanwhile, it was found that some gene markers associated with breast cancer were also present in the yellow module, such as BRCA1 and CCNB1." (PMID 41394782, 2025). "CCNB1 overexpression correlates with adverse prognosis in diverse tumors, notably hepatocellular carcinoma, breast cancer, and bladder cancer." (PMID 41614789, 2025).
breast carcinoma (continued). "Together, these results illustrate that D-arabinose has a pivotal role in modulation of cell cycle progression by regulating the activity of CDK1, Cyclin B1, p21, and p27 in breast cancer cells." (PMID 38789954, 2024). "As Aurora-A interacts with cyclin B1, inhibiting cyclin B1 degradation, targeting the Aurora-A–cyclin B1 axis suggests promising new approaches for obesity-induced breast cancer prevention and treatment resistance." (PMID 38999849, 2024). "The results revealed that total protein expression of CCNB1 was elevated in nine types of cancer, including breast cancer, GBM, HNSC, hepatocellular carcinoma, LUAD, LUSC, ovarian cancer, UCEC, and PAAD." (PMID 38581717, 2024). "Overexpression of CDC20 and CCNB1 has been identified in tumor tissues from breast cancer, glioblastoma, ovarian cancer, and ductal adenocarcinoma." (PMID 39795587, 2024). "Together, these results illustrate that d-arabinose has a pivotal role in modulation of cell cycle progression by regulating the activity of Cyclin B1, p21, and p27 in breast cancer cells." (PMID 38755221, 2024). "A recent analysis of breast cancer samples integrated in The Cancer Genome Atlas (TCGA) revealed that KIF2C, along with two cell cycle master regulators CCNB1 (cyclin B1) and Plk1, is a promising target for breast cancer therapy." (PMID 38344808, 2024). "Cyclin B1 overexpression has been reported in breast cancer, cervical cancer, gastric cancer, colorectal cancer, SCC of the HNC and non-small cell lung cancer, and its upregulation is closely associated with poor prognosis in various cancer types." (PMID 37759511, 2023). "Downregulation of cyclin B1 is consistent with studies showing that this gene plays a role in inhibiting proliferation of several breast cancer cell lines." (PMID 37049472, 2023). "An increasing number of studies have shown that CCNB1 is closely related to the abnormal proliferation of cells and the occurrence of tumors, such as CCNB1 overexpression in liver cancer, breast cancer, esophageal cancer, and cervical cancer." (PMID 37758792, 2023). "It has been shown that in lung cancer, breast cancer, cervical cancer, and melanoma and esophageal squamous cell carcinoma, CCNB1 expression is relatively high." (PMID 37671046, 2023). "Mechanistically, the induction of G2/M arrest in human breast cancer cells is due to diminished cyclin B1 expression." (PMID 37242455, 2023). "It has been shown that CCNB1 is a prognostic factor for overall survival and metastasis-free survival in breast cancer." (PMID 37592341, 2023). "This study concluded that d-limonene suppresses the proliferation of breast cancer cells by inducing G2/M phase arrest via deregulation of Cyclin B1/CDK1." (PMID 36307489, 2022). "A previous study showed that circRNA CCNB1 (circ-CCNB1) suppresses cell migration, invasion, and proliferation by inhibiting the formation of the CCNB1-Cdk1 complex in breast cancer cells." (PMID 35731831, 2022). "Especially, overexpression of CCNB1 and PLK1 are strongly associated with the low survival rate of breast cancer patients, demonstrating their potentiality as prognostic markers." (PMID 35456460, 2022). "The combination of CCNB1 and paclitaxel increases the apoptosis of breast cancer cells and enhances paclitaxel’s antiproliferative effect." (PMID 35456460, 2022).